DDX46 (DEAD-box helicase 46)
Description:
Component of the 17S U2 SnRNP complex of the spliceosome, a large ribonucleoprotein complex that removes introns from transcribed pre-mRNAs. The 17S U2 SnRNP complex (1) directly participates in early spliceosome assembly and (2) mediates recognition of the intron branch site during pre-mRNA splicing by promoting the selection of the pre-mRNA branch-site adenosine, the nucleophile for the first step of splicing. Within the 17S U2 SnRNP complex, DDX46 plays essential roles during assembly of pre-spliceosome and proofreading of the branch site.
Synonyms: KIAA0801; FLJ25329; PRPF5; Prp5
Tractability: Small molecule: a structure with a bound ligand is known. PROTAC: UniProt records ubiquitination sites on it; ubiquitination databases record sites on it; its protein half-life has been measured.
Gene: Protein-coding gene on chromosome 5 (134,758,771 to 134,831,121, forward strand). Ensembl gene ENSG00000145833.
Subcellular location: Nucleus speckle; Nucleus, Cajal body
Subcellular location (Human Protein Atlas): Nuclear speckles; Nucleoli fibrillar center
Pathways (Reactome):
Metabolism of RNA: mRNA Polyadenylation; mRNA Splicing - Major Pathway
Chromatin organization: CHD1 and CHD2 subfamily
Disease: Dengue Virus-Host Interactions
Gene Ontology:
Molecular function: protein binding; RNA binding; RNA helicase activity; ATP binding; ATP hydrolysis activity; nucleic acid binding
Biological process: mRNA splicing, via spliceosome; U2-type prespliceosome assembly
Cellular component: nuclear speck; nucleus; U2-type spliceosomal complex; nucleoplasm; spliceosomal complex; U2 snRNP; Cajal body
Genetic constraint (gnomAD): Loss-of-function variants: 27 observed, 127.52 expected, observed/expected ratio (o/e) 0.21, 90% interval 0.16 to 0.29. The upper end of that interval is the gene's LOEUF score, 0.29, which puts it in group 1 of 6, group 1 being the genes least tolerant of losing a copy. Missense variants: 597 observed, 1,253.6 expected, observed/expected ratio (o/e) 0.48, 90% interval 0.44 to 0.51. Synonymous variants: 406 observed, 407.76 expected, observed/expected ratio (o/e) 1, 90% interval 0.92 to 1.08.
Homologues: Orthologues: chimpanzee DDX46 (99% identical), macaque DDX46 (99% identical), dog DDX46 (99% identical), guinea pig DDX46 (99% identical), rabbit DDX46 (99% identical), mouse Ddx46 (99% identical), pig DDX46 (99% identical), rat Ddx46 (98% identical), tropical clawed frog ddx46 (90% identical), zebrafish ddx46 (82% identical). Paralogues in human: DDX42 (21% identical), DDX23 (21% identical), DDX43 (19% identical), DDX17 (19% identical), DDX3X (18% identical), DDX3Y (18% identical), DDX41 (18% identical), DDX5 (18% identical), DDX53 (18% identical), DDX4 (17% identical), DDX54 (16% identical), DDX59 (16% identical), and 26 more.
Diseases named in the same sentence as DDX46 in open-access papers:
DDX46 is named in the same sentence as 15 diseases in open-access papers, as found by Europe PMC text mining. Sharing a sentence is not in itself a finding about the gene and the disease. The quoted sentences say what the papers report.
viral infection (6 papers, 2021 to 2026). "During viral infection, the RNA helicase DDX46 binds more strongly to transcripts, which encode MAVS, TRAF3, and TRAF6, and other antiviral protein, resulting in the recruitment of ALKBH5 to demethylate these transcripts." (PMID 36176733, 2022). "One of nuclear DDX family members, DDX46 can inhibit the production of type I interferon after viral infection." (PMID 34103054, 2021). "While DDX46 has been shown to sequester demethylated innate immune transcripts in the nucleus and dampen interferon (IFN) production, the mechanisms underlying its regulation during viral infection remain unclear." (PMID 41854249, 2026). "DDX46, or DEAD-Box Helicase 46, is a protein that negatively regulates the innate antiviral response to viral infection." (PMID 40431638, 2025). "After viral infection, ALKBH5 is recruited by DDX46 through DDX46’s DEAD helicase domain to demethylate those m6A-modified antiviral transcripts." (PMID 34103054, 2021).
osteosarcoma (5 papers, 2020 to 2022). A usually aggressive malignant bone-forming mesenchymal neoplasm, predominantly affecting adolescents and young adults. "DDX46 is abnormally expressed in osteosarcoma tissues and cells, promoting cell growth and invasion." (PMID 34573320, 2021). "The expression of DDX46 is upregulated in colorectal carcinoma, esophageal squamous cell carcinoma, gastric cancer, and osteosarcoma cells, and knockdown of DDX46 inhibits cancer cell proliferation, invasion and induces cell apoptosis." (PMID 34207140, 2021). "Knockdown of DDX46 obviously inhibits osteosarcoma cell proliferation and suppresses migration and invasion in osteosarcoma cells." (PMID 33817228, 2020). "Knockdown of DDX46 inhibited osteosarcoma cell proliferation and tumor growth in vivo." (PMID 36160006, 2022).
esophageal squamous cell carcinoma (4 papers, 2020 to 2022). Esophageal squamous cell carcinoma (ESCC) is a type of esophageal carcinoma (EC) that can affect any part of the esophagus, but is usually located in the upper or middle third. "The expression of DDX46 is increased in esophageal squamous cell carcinoma and colon cancer tissues, promoting cell growth and inhibiting apoptosis." (PMID 34573320, 2021). "DDX46 knockdown leads to decreased proliferation in esophageal squamous cell carcinoma cells." (PMID 33817228, 2020). "DDX46 silencing arrested cell cycle at G1 phase in esophageal squamous cell carcinoma (ESCC) cell lines." (PMID 35723050, 2022).
esophageal cancer (1 paper, 2025). A primary or metastatic malignant neoplasm involving the esophagus. "By integrating bioinformatics, experimental validation, and clinical correlation analyses, we identified six SFs (CRNKL1, SNRPB2, RBMX2, DDX46, PPWD1, and CFAP20) that are aberrantly overexpressed in esophageal cancer and tightly linked to poor prognosis." (PMID 40282339, 2025). "Exon 11 skipping of CTTN occurred after knockdown of most survival-related SFs (CRNKL1, SNRPB2, PPWD1, RBMX2, and DDX46), while exon 11 inclusion was observed in esophageal cancer in comparison to normal tissue, both in the TCGA database and in our own full-length sequencing data." (PMID 40282339, 2025).
lung adenocarcinoma (1 paper, 2021). A carcinoma that arises from the lung and is characterized by the presence of malignant glandular epithelial cells. "Interestingly, a study previously reported that DDX46 interacts with SMC4, which was identified substantially involved in lung development and highly related with the progression of lung adenocarcinoma." (PMID 34573320, 2021).
cancer (14 papers, 2012 to 2025). A tumor composed of atypical neoplastic, often pleomorphic cells that invade other tissues. "This analysis identifies important roles of DDX42 N-plug and DDX46 acidic loop in mediating the effects of cancer mutations in SF3B1." (PMID 36797247, 2023). "In contrast to DDX42, three SF3B1 residues (Asp894, Tyr898 and Glu902) that interact with DDX46 only are mutated in cancer." (PMID 36797247, 2023). "CFAP20, PPWD1, and DDX46 were positively correlated with cancer-associated fibroblasts (CAFs)." (PMID 40282339, 2025). "Cancer-driving mutations of SF3B1 target the residues in the RNA path that directly interact with DDX42 and DDX46." (PMID 36797247, 2023). "Together with structure-guided biochemical analysis, our study reveals a coherent picture on the roles of DDX42 and DDX46 in U2 snRNP assembly and provide insights into SF3B1 cancer mutations." (PMID 36797247, 2023). "Remarkably, all seven residues are located in the RNA path and directly recognize the N-plug of DDX42 and the acidic loop of DDX46; substitutions of these residues in cancers impair the binding of both DDX4246 and DDX4623." (PMID 36797247, 2023). "For example, DDX46 and PTPRD have been associated with several types of cancer in various studies, but in our study only a measure of intolerance against loss of function mutations provided by gnomAD indicated an involvement in core biological processes." (PMID 34605899, 2022). "Among them, we want to highlight DDX3 as a confirmed target for cancer and antiviral therapy, while others, like DDX46, DHX9 and DDX5, are still poorly studied in this context." (PMID 33804185, 2021). "DDX46 is a kind of RNA helicase that has been found to regulate cell proliferation and metastasis of cancer cells." (PMID 33817228, 2020). "In addition, seven SF3B1 residues that interact with both DDX46 and DDX42 are targeted for mutations in cancer, including the most frequently mutated residue Lys700." (PMID 36797247, 2023). "Our study suggests distinct mechanisms of DDX42 and DDX46 in cancer development." (PMID 36797247, 2023). "DDX46 is a kind of RNA helicase that has been found to regulate cancer cell metastasis." (PMID 33817228, 2020). "Some of these proteins were previously connected to different cancer types, including CLL, while four other highly expressed proteins were not previously reported to be associated with cancer, and here, for the first time, DDX46 and AK3 are linked to CLL." (PMID 27078856, 2016). "Additionally, unlike both SUGP1 and DHX15, DDX46 is not known to harbor any cancer-associated mutations that recapitulate mutant SF3B1 missplicing." (PMID 37977822, 2023). "While DDX46 functions as an RNA splicing factor similar to DDX42, detailed reports on the biological functions of SMNDC1 and UNK in cancer are currently limited." (PMID 40831000, 2025). "Conversely, MTA2, DDX46, CDCP1, and CELF1, which have been reported to play a role in at least one of these processes in CRC, are known to promote cancer." (PMID 37510319, 2023).
tumor (2 papers, 2022 to 2025). "Additionally, several survival-related SFs (CRNKL1 and DDX46) were positively correlated with tumor purity, suggesting lower tumor immune infiltration." (PMID 40282339, 2025).
DDX46 also shares sentences with these, for which no sentence is quoted: breast carcinoma (1 paper); chronic lymphocytic leukemia (1); colon cancer (1); colorectal carcinoma (1); COVID-19 (1); gastric cancer (1); melanoma (1); preeclampsia (1).